GATA3 (GATA binding protein 3)
Diseases named in the same sentence as GATA3 in open-access papers (continued):
Sharing a sentence is not in itself a finding about the gene and the disease.
breast carcinoma (continued). "Here, we synergistically combine mathematical modeling and perturbation experiments to unravel the transcriptional regulatory connections in the ERα–GATA3 network in ERα-positive breast cancer cell lines." (PMID 24792166, 2014). "Methylation for GATA3 was found in 5/8 (63%) breast cancer cell lines, as expected from previous reports describing GATA3 methylation in breast cancer tissue samples." (PMID 24549248, 2014). "In accordance with the population effect, when compared to normal mammary epithelial cells, GATA3 transcript levels are elevated in the luminal breast cancer lines and decreased in BLBC lines." (PMID 25410484, 2014). "Out of the top ten mutated genes in the large breast cancer investigation of The Cancer Genome Atlas (TCGA), we found mutations in seven of these (PIK3CA, GATA3, MAP3K1, MLL3, CDH1, PTEN, TBX3)." (PMID 24998755, 2014). "One of the TF regulators shared among both the Luminal A and Luminal B groups is GATA3, a regulator of ERα signaling that is required for the luminal type of breast cancer." (PMID 25183703, 2014). "Given the association of early neoplasias with ER + breast cancers, we wished to further characterize two important transcription factors, FOXA1 and GATA3, thought to act upstream of ER in the estrogen response pathway." (PMID 24887547, 2014). "hMEC are a mixed myoepithelial/luminal population, only the latter of which express GATA3; MCF7 is a luminal breast cancer line, which overexpresses high levels of GATA3, and thus is a convenient line to use for ChIP of the endogenous protein." (PMID 25410484, 2014). "GATA3 overexpression has been observed in breast carcinomas by complementary DNA microarray analysis." (PMID 24504018, 2014). "Accordingly, cyclin A2 was found to be significantly downregulated in MDA-MB-231 breast cancer cells engineered to overexpress GATA3." (PMID 25479686, 2014). "Many studies have implicated GATA3 as a strong positive prognostic marker for breast cancer patients, with ERα-positive breast cancers having high GATA3 expression and well-differentiated cell morphology." (PMID 24792166, 2014). "These genes, FOXA1, GATA3, and MYB, all showed greater mutation rates in ER+/luminal cancers relative to other breast cancer subtypes and, here, possessed up-regulated expression in early neoplasias relative to normal." (PMID 24887547, 2014). "No other protein classified patients by clinically relevant groups at similar statistical significance in the roughly 1,000 patients tested, adding to accumulating evidence that GATA3 plays an imperative role in the biology of breast cancer." (PMID 25410484, 2014). "As a first step in characterizing the involvement of GATA3 in luminal breast cancer, we identified its target genes in normal and cancer breast cells." (PMID 25410484, 2014). "To test the effects of GATA3 on tumorigenesis, we, therefore, tested its effect on these genes in normal and luminal breast cancer cells." (PMID 25410484, 2014). "In a mouse model of breast cancer, GATA3 was found to inhibit the metastatic seeding of breast cancer cells." (PMID 24504018, 2014). "Several studies demonstrated that GATA3 expression holds independent prognostic value of a favorable outcome in breast cancer patients." (PMID 25479686, 2014). "In contrast, GATA3 expression was lower relative to normal tissue in a subset of the group 2 cohort, a cohort with improved overall survival for patients with TN breast cancer." (PMID 24426833, 2014). "The majority of breast cancers arise from luminal epithelial cells; therefore, GATA3 appears to control a set of genes involved in the differentiation and proliferation of breast cancer cells." (PMID 24748983, 2014).
breast carcinoma (continued). "Protein stability controlled by action of the 26S proteasome is integral to the biology of ERα, which is found in close proximity to GATA3 at many genomic locations in breast cancer cells." (PMID 24758297, 2014). "Strikingly, while mutations of GATA3 in the congenital disorder HDR syndrome are found throughout the protein, breast cancer specific mutations occur almost exclusively in exons 5 and 6 (TCGA)." (PMID 24758297, 2014). "The altered regulatory effect of GATA3 in breast cancer cells predicts that a distinct phenotype should result in normal and cancer cells following GATA3 expression." (PMID 25410484, 2014). "In breast cancer, Gata3 has been shown to function as a “pioneer factor” to help open up condensed chromatin and recruit other TFs." (PMID 25299227, 2014). "GATA3 is involved in a positive cross-regulatory loop with estrogen receptor-α (ERα) where they both serve as markers for luminal breast cancer." (PMID 24758297, 2014). "We utilized two luminal breast cancer cell lines, MCF7 harboring a heterozygous frameshift mutation in ZnF2, and T47D carrying wild-type version GATA3." (PMID 24758297, 2014). "Grouped by gene, many of these novel mutations comprised large gains in absolute counts and in percent increase, including MAP3K1 and GATA3 in breast cancer, and NOTCH2 and CDKN2A in lung cancer." (PMID 24970867, 2014). "The requirement of GATA3 for the development of the mammary gland and for the maintenance of the luminal cell fate suggested potential implications for GATA3 in the breast cancer scenario." (PMID 25479686, 2014). "GATA binding protein 3 (GATA3) is a regulator of mammary luminal cell differentiation, and an estrogen receptor (ER) associated marker in breast cancer." (PMID 25410484, 2014). "Here we characterized the regulatory connections between ERα and GATA3 in ERα-positive breast cancer cell lines." (PMID 24792166, 2014). "In summary, a critical role is demonstrated for GATA3 within the networks that govern breast cancer progression." (PMID 25410484, 2014). "Since, in luminal breast cancer models, GATA3 induces differentiation, we postulate that our observations reflect proliferation of an existing TIC population rather than active de-differentiation." (PMID 25410484, 2014). "Given the ERα-dependent classification of breast cancers into two major subtypes (ER-positive and ER-negative), we naïvely expected that a quantitative characterization of the ERα–GATA3 network would reveal a bistable switch." (PMID 24792166, 2014). "A systematic identification of molecular pathways regulated by GATA3 would thus highlight and uncover major processes governing breast cancer development." (PMID 25410484, 2014). "Analysis of a publicly available microarray dataset showed that cyclin A2 was the only member of the cyclin family that was significantly downregulated upon GATA3 overexpression in MDA-MB-231 breast cancer cells." (PMID 25479686, 2014). "GATA3 has been shown in mouse model of breast cancer to maintain tumor differentiation, suppress dissemination and inhibit metastasis." (PMID 24758297, 2014). "Upon subsequent transformation, however, a shift concomitant with our observations in luminal breast cancer cells occurred, namely, GATA3 upregulates expression of these genes." (PMID 25410484, 2014). "Further studies investigating the regulatory mechanism of GATA3 transcriptional activity are required to design novel strategies against breast cancer cell growth and differentiation." (PMID 24748983, 2014). "Here, we aimed to acquire a systemic view of the role played by GATA3 in luminal breast cancer progression." (PMID 25410484, 2014). "GATA3 has been shown to suppress lung metastasis from mouse and human mammary tumors by a mechanism that involves cell fate specification." (PMID 24867881, 2014).
breast carcinoma (continued). "The transcription factor GATA3 critically determines luminal lineage specification of mammary epithelium and is widely considered a tumor and metastasis suppressor in breast cancer." (PMID 24205108, 2013). "We identified many known drivers of breast cancer and other types of cancer, in the female dataset (e.g. GATA3, CCNE1, GRB7, CDK4)." (PMID 24194916, 2013). "Many known drivers of breast cancer, including GATA3, CCNE1, CDK4 and GRB7, as well as known drivers for other tumor types were identified among the FBC candidate drivers." (PMID 24194916, 2013). "The results of this study demonstrate for the first time that an interplay between TGFß signaling and GATA3 also exists in breast cancer." (PMID 23577196, 2013). "Our analysis leads us to propose that luminal differentiation, as assessed by estrogen receptor and GATA3 expression levels, is only infrequently lost during the process of regional lymph node colonization by breast cancer cells." (PMID 24205108, 2013). "GATA3 is a transcription factor that regulates immune cells, and has long been known to be involved in breast cancer tumorigenesis." (PMID 23717195, 2013). "Our observations corroborate that metastasis to local and regional lymph nodes of luminal-type breast cancer only infrequently involves a decline in the expression of ER or GATA3." (PMID 24205108, 2013). "We applied REACTIN to compare ER+ with ER- samples in ten breast cancer datasets and successful detected the activity difference of ER alpha, FOXA1 and GATA3 between ER+ and ER- breast cancer subtypes." (PMID 23885756, 2013). "Recently, a novel role for GATA3 was discovered, whereby GATA3 suppresses breast cancer metastasis through inhibition of E-cadherin promoters." (PMID 23717195, 2013). "Gata3 regulates tumor differentiation, suppresses tumor metastasis in breast cancer and increased Arnt (HIF-1) activity promotes tumor progression." (PMID 22952821, 2012). "Specifically, we show that TCF7L2 has highly cell type-specific binding patterns, co-localizes with different factors in different cell types, and can be tethered to the DNA by GATA3 in breast cancer cells." (PMID 22951069, 2012). "Studies of human breast cancers have shown that GATA3 is expressed in early stage, well-differentiated tumors but not in advanced invasive cancers." (PMID 22951069, 2012). "Most importantly, STAT1-/- mammary tumors express elevated levels of ERα, PR, GATA3, AREG, XBP1, and FOXA1, all of which are regulated by the transcriptional control of ERα." (PMID 22264274, 2012). "We directly tested the role of GATA3 in regulating the glutamine phenotype in breast cancer cell lines." (PMID 21852960, 2011). "The ER induced inhibitor of SNAIL1, MTA3, and GATA3, which inhibits breast cancer metastasis through the reversal of EMT, were also significantly lower." (PMID 21713035, 2011). "A cohort of ERα-negative patients was therefore studied in order to evaluate the predictive importance of FOXA1 and GATA-3 expression in this subset of breast carcinomas." (PMID 19549328, 2009). "FOXA1 was a significant predictor of good outcome in breast cancer, whereas GATA-3 was an important luminal marker." (PMID 19549328, 2009). "In breast cancer, high GATA-3 expression correlates with low tumour grade and slow proliferation rates, corresponding to our results." (PMID 19707195, 2009). "In the present study we provide an immunohistochemical approach studying FOXA1 and GATA-3 expression, in order to predict the tumour behaviour of breast cancer patients." (PMID 19549328, 2009).
breast carcinoma (continued). "Among all of the molecular subgroups of breast cancer, the luminal A subtype has a relatively favourable outcome and the highest GATA-3 and ERα expression levels, compared with luminal B and basal-like breast carcinomas." (PMID 19549328, 2009). "FOXA1 and ERα have been explored as potential participants involved in mammary tumours together with another gene, GATA-3, which regulates the lineage determination and differentiation of many cells types." (PMID 19549328, 2009). "Specifically, in the luminal A subtype of breast cancer GATA3 has both a favorable prognostic outcome, and the highest ERα and GATA3 expression of all breast tumours." (PMID 18533032, 2008). "Meanwhile, GATA3 is also a transcription factor serving as a curial component in the tumorigenesis of ER+ breast cancer, and is involved in growth control and maintenance of the differentiated state in epithelial cells." (PMID 21655371, 2008). "In an elegant series of experiments utilizing MMTV-PyMT (polyoma middle T antigen) mice it was first shown that GATA3 expression was downregulated with the transition from adenoma to carcinoma in mammary tumours, and the expression was lost in lung metastases." (PMID 18533032, 2008). "In genome-wide expression profile studies from our laboratory we observed that the expression of GATA3 is highly correlated with estrogen receptor-α (ERα) status in breast carcinomas similar results were reported by others." (PMID 17078870, 2006). "Our study provides evidence indicating that GATA3 is probably a mediator for the transcriptional upregulation of MUC1 expression in some breast cancers." (PMID 17078870, 2006). "Specifically, GATA3 was detected as being expressed in 90% of the breast cancer cases (42 out of 47) according to SAGE database analyses." (PMID 17078870, 2006). "Transcriptome profile analyses demonstrated that GATA3 expression is strongly correlated with ERα status in breast cancer." (PMID 17078870, 2006). "GATA3 knockdown assays led to a significant decrease in MUC1 protein expression in MCF7 breast cancer cells, strongly suggesting an involvement of GATA3 in the modulation of MUC1 expression." (PMID 17078870, 2006). "To explore whether our DNAzymes could knock down GATA3, we designed constructs targeting a GU junction in exon 6 of the GATA3 transcript (nucleotides 2490–2491) and transfected MCF7 breast cancer cells with Dz46, tC3, and tC3+ variants." (PMID 41495895, 2026). "Activation of GATA3 is capable of restricting the motility of luminal breast cancer cells." (PMID 40771813, 2025). "Our findings suggest that this group of breast cancers could potentially be targeted with a novel therapeutic approach aimed at reactivating GATA3 through DNA methylation reprogramming or the use of DNA demethylating agents." (PMID 40585280, 2025). "This significant morphological overlap necessitates meticulous clinicopathological correlation and a comprehensive immunohistochemical workup, as conventional markers such as CK7, ER, PR, and GATA3 lack specificity due to their frequent expression in breast carcinomas." (PMID 40969274, 2025). "The GATA3–LOFDEL group represents 8.6% of all breast cancer samples in the TCGA–BRCA dataset." (PMID 40585280, 2025). "GATA-3 positivity is present in 100% of cases of invasive lobular carcinoma of the breast and in 96% of cases of invasive ductal carcinoma of the breast and is considered a marker for breast cancer." (PMID 40919150, 2025). "GATA3 is a transcription factor that is involved in the luminal differentiation of breast epithelium, and it also plays a role in the maintenance of the luminal cell identity and the suppression of the basal cell phenotype in breast cancer." (PMID 40003882, 2025). "In addition to these markers, mammaglobin, GCDFP-15, GATA3, and lactalbumin are also useful in supporting the diagnosis of primary breast cancer." (PMID 40433060, 2025).
breast carcinoma (continued). "Additionally, AR expression is often co-regulated with other factors, such as GATA-3, a transcription factor that plays a role in breast cancer differentiation and prognosis." (PMID 40286049, 2025). "In addition to breast cancer, GATA3 positivity has been reported in other tumors such as urothelial carcinoma, renal cell carcinoma, gynecological tumors, salivary gland tumors, hematologic malignancies, and skin cancers." (PMID 40605856, 2025). "The GATA3–METH group represents 6.8% of all breast cancer samples in the TCGA–BRCA dataset." (PMID 40585280, 2025). "GATA3 mutations are among the most common alterations in hormone receptor-positive (HR+) breast cancer (BC), yet these have no targeted therapies." (PMID 40439821, 2025). "GATA3 is a transcription factor, and its prognostic significance may vary across different molecular subtypes of breast cancer." (PMID 41026783, 2025). "We have shown that the loss of GATA3 is associated with aggressive tumor features in breast cancer, also independent of ER." (PMID 41024411, 2025). "In both hormone-dependent breast and prostate cancers, FOXA1 forms a triumvirate with a GATA protein and an NR (GATA3 and ER in breast cancer; GATA2 and AR in prostate cancer) and is the foundational protein in these cancers due to its ability to create new enhancer elements." (PMID 41168397, 2025). "In the prognostic stratification analysis, this study further demonstrated that the combined model incorporating 3.0T HR-MRI parameters, ultrasound imaging features, and GATA3 protein expression exhibited superior accuracy in predicting the prognosis of breast cancer patients." (PMID 40881878, 2025). "In our study, the most useful marker for identifying breast carcinoma was GATA-3." (PMID 40751531, 2025). "Prior analyses of the GATA3 mutational landscape have been performed on tissue sequencing data from primary breast cancers, where patients have not been exposed to therapeutic pressures." (PMID 40439821, 2025). "GATA3 is a very specific marker for breast cancer (and urothelial carcinomas)." (PMID 40530017, 2025). "Moreover, we found some known stemness‐related genes among the top 50 genes representing the stemness programme, such as the transcription factor GATA3, which has been identified as a robust predictor of clinical outcome in human luminal breast cancer." (PMID 39630113, 2025). "For example, the mechanisms underlying GATA3 downregulation in aggressive breast cancers are not fully understood, which complicates the development of targeted therapies." (PMID 39768217, 2024). "GATA3 is highly expressed in luminal breast cancers, but hardly detectable in BLBCs." (PMID 38627785, 2024). "In a minor series of 28 ER-positive cases of breast cancer, lack of GATA3 expression was associated with unresponsiveness to hormonal therapy." (PMID 39242600, 2024). "Therefore, an important functional consequence of androgen-induced interaction between AR and GATA3 is modulation of the GATA3 cistrome to facilitate regulation of AR target genes in ER+ breast cancer cells." (PMID 38317241, 2024). "The interaction between AR and GATA3 we discovered herein in breast cancer may in part explain why AR has distinct roles in breast compared to prostate tissues." (PMID 38317241, 2024). "GATA3 is required for HR to repair DNA double-strand breaks in breast cancer." (PMID 38745917, 2024). "It has recently been reported that depletion of GATA3 may impair HR-mediated DNA damage repair by downregulating CtIP in breast cancer cells in vitro." (PMID 38627785, 2024).